HLA-G (major histocompatibility complex, class I, G)
Diseases named in the same sentence as HLA-G in open-access papers (continued):
Sharing a sentence is not in itself a finding about the gene and the disease.
cancer (continued). "In our study, the HLA-G expression was not affected by cancer treatment, as we used samples from patients before the initiation of systemic therapy." (PMID 38391781, 2024). "HLA-G and its receptors are considered as a new immune checkpoint and potential targets for cancer immunotherapy, and several antibodies targeting HLA-G, LILRB1, or LILRB2 are currently in clinical trials for cancer treatment." (PMID 39237366, 2024). "In recent years, non-classical HLAs—including HLA-E, HLA-F, HLA-G, and HLA-H—have emerged as critical players in the immune landscape of cancer due to their diverse and less conventional functions in immune modulation." (PMID 39766165, 2024). "In the present study, we found that HLA-G was more highly expressed in cancer tissues than in non-cancerous tissues." (PMID 38638429, 2024). "Along similar lines, IFNγ signaling can also boost the expression of non-classical MHC class Ia genes, such as HLA-G, -E and -F, which are known to endow cancer cells with ability to evade CTL and NK cell responses." (PMID 37762241, 2023). "Similar to HLA-G, CD46 was found to be upregulated in a variety of cancer cells." (PMID 35924232, 2022). "Similarly, patients with vulvar squamous cell carcinoma (VSCC) showed a higher expression of HLA-G and IDO in cancer tissue than in surrounding normal tissue." (PMID 35328349, 2022). "Some HLA-G-based strategies have been proposed for cancer immunotherapy, but none of them has reached the market yet." (PMID 36559230, 2022). "In particular, ovarian and gastric cancer cell lines, after differentiation to adipocyte or neurocyte, showed a reduced expression of the CD90 stem cell marker, thus decreasing the percentage of cancer stem cells (CSC), and an increased expression of both HLA-G and PD-L1." (PMID 35328349, 2022). "Consequently, blocking ILT2 maintained the lytic effect of NK cells in the presence of HLA-G, making the use of this anti-ILT2 a promising therapy for cancer." (PMID 35154112, 2022). "Human Leukocyte Antigen-G (HLA-G), a polymorphic non-classical HLA (HLA-Ib) with immune-regulatory properties in cancers and infectious diseases, presents both membrane-bound and soluble (sHLA-G) isoforms." (PMID 35204759, 2022). "The human HLA-G is a member of the MHC-Ib family, which was first discovered in extravillous cytotrophoblasts and expressed in several pathological situations, such as cancers and inflammatory and autoimmune diseases." (PMID 36437782, 2022). "HLA-G is a nonclassical histocompatibility class I molecule that plays a role in immune vigilance in cancer and infectious diseases." (PMID 35774498, 2022). "The current findings may provide novel insights for blockade of the HLA-G/ILT axis, which holds potential for the development of more effective antitumor treatments in cancers." (PMID 34276642, 2021). "There are classical forms, HLA-A, HLA-B, and HLA-C, and non-classical forms, HLA-G, HLA-E, HLA-F, and HLA-H, of this protein; both have been identified in cancer with diverse roles." (PMID 34359613, 2021). "Both univariate (HR = 2.01, 95% CI: 1.48 ~ 2.72) and multivariate (HR = 2.69, 95% CI: 2.03 ~ 3.55) analyses revealed that HLA-G expression was significantly correlated with poor overall survival (OS), regardless of the cancer type or antibody used." (PMID 34055611, 2021). "In our opinion, it can therefore not be concluded with certainty that HLA-G is an immune checkpoint in all these carcinoma types." (PMID 34361031, 2021). "Human leukocyte antigen G (HLA-G) is a non-classical human leukocyte antigen (HLA) class I protein that interacts with inhibitory receptors and is commonly overexpressed in various cancers, thereby establishing itself as an inhibitory checkpoint immune ligand." (PMID 32019184, 2020).
cancer (continued). "Signaling pathway between human leukocyte antigen (HLA)-G and immune inhibitory receptors immunoglobulin-like transcript (ILT)-2/4 has been acknowledged as one of immune checkpoints, and as a potential target for cancer immunotherapy." (PMID 33329527, 2020). "When cancer cells (i.e., A549, HCC827, CNE2 and HONE1 cells) were transiently transfected with miR-19a or miR-19b-1 mimics, qRT-PCR data revealed a general downward trend in the expression profile of the MHC Class I genes (such as HLA-B, HLA-F, HLA-G)." (PMID 32308549, 2020). "Like HLA-E, it is also thought to mediate important immunosuppressive functions, but unlike HLA-G, its significance in cancers is not yet established." (PMID 29587858, 2018). "Recent studies showed that the expressions of HLA-G mRNA and protein were upregulated in HLA-G-negative cancer cells via HIF-1α under hypoxic conditions." (PMID 30061885, 2018). "Recently, the nonclassical MHC class I molecule HLA-G has emerged as an important regulator of immune responses and a potential mediator of cancer immune resistance." (PMID 29464090, 2018). "Its emerging role further emphasizes the importance of studying the impact of immune system regulation in cancer, in particular the influence of the nonclassical human leukocyte antigen-G (HLA-G) in the mechanisms involved in tumorigenesis." (PMID 28781970, 2017). "Albeit high blood levels of soluble forms of HLA-G have concordantly been related to cancer, the prognostic relevance of soluble HLA-G in the blood has not always been established as an independent marker in terms of disease progression and survival." (PMID 27199995, 2016). "The second is the competence of cancer cells in regulating the expression of the non-classical HLA class I molecules such as HLA-G." (PMID 26633805, 2015). "Nevertheless, ectopic expression of HLA-G is commonly observed in pathological situations such as cancer, not rejected allografts, virus infections, autoimmune diseases, and inflammation." (PMID 24800261, 2014). "Another non-classical HLA-I molecule, HLA-G, has been identified in diverse malignancies including cancers and has received a lot of attention in recent publications." (PMID 21712991, 2011). "All these data indicate that carcinoma-expressing HLA-G could be one of important mechanisms for inhibition of both CD8+CTL and NK cell mediated anti-carcinoma immunity." (PMID 21255410, 2011). "In contrast to the classical HLA class I antigens, which have been extensively investigated, the immune-modulatory roles and clinical significance of the non-classical HLA class I antigens—particularly HLA-G—have attracted increasing attention in cancer biology." (PMID 41194925, 2025). "On the other hand, HLA-G is not a prognostic factor of survival for other types of cancers." (PMID 38877399, 2024). "Notably, the levels of expression of these genes, added to six other genes involved in mitochondria activity (TST, NSUN3, GLMP and PTCD2), were reduced following the expression of HLA-G in the RCC7 cells, consistent with mitochondrial impairment found in many types of cancer, particularly in ccRCC." (PMID 39358558, 2024). "However, not all published works are equally consistent and, although they show HLA-G expression in cancer, do not allow to correlate HLA-G with certain types of cancer." (PMID 35154112, 2022). "Interestingly, cancer cells interfere with these phases through an aberrant expression of the nonclassical HLA-G during the development of an overt malignancy." (PMID 36437782, 2022). "Although neoadjuvant chemotherapy (NACT) has been a successful tool to improve overall survival (OS), there is growing evidence that various environmental factors like the non-classical human leukocyte antigen-G (HLA-G) promotes cancer invasiveness and metastatic progression." (PMID 35095919, 2021).
cancer (continued). "Similarly, the HLA-G-blocking antibody remarkably enhanced the ADCC activity of NK cells with respect to HER2-positive cancer cells, but not those that negligibly expressed HER2." (PMID 34158475, 2021). "Overall, HLA-G expression did not univocally result in poor clinical outcome of carcinoma patients." (PMID 34361031, 2021). "However, HLA-G expression was not correlated with cancer relapse, metastasis, node invasion or with mortality rate." (PMID 32922387, 2020). "Notably, the percentage of HLA-G expressing malignant cells depends on the type of cancers, and expression levels vary from negative to totally positive among different types of cancers." (PMID 30319626, 2018). "In the context of the immunomodulatory role of HLA-G as an immune checkpoint molecule in cancer and the complex regulation of soluble HLA-G protein expression related to HLA-G 3′UTR SNPs and haplotypes, our findings represent new advances in the understanding of HLA-G." (PMID 28653974, 2017). "HLA-G is not a tumorigenic molecule per se, but it could contribute to tumorigenesis if expressed by cancer stem cells or precancerous cells, shielding them from immune destruction during their evolution processes." (PMID 25887663, 2015). "However, it is not known whether high levels of HLA-G and/or SPAG9 in primary cancers could predict patients at risk of developing BM." (PMID 36780531, 2023). "However, a recent study has showed that HLA-G expression did not significantly correlate with poor clinical outcome of cancer patients, which indicated that HLA-G expression might not necessarily participate in immunosuppression in carcinogenesis." (PMID 35185887, 2022). "Our search for mechanisms underlying the induction of HLA-G showed that both HHV-6A/6B infection and U94 transfection/protein treatment are potently upregulating ATF3, which so far was known to be involved in immune response, inflammation and cancer, but not in HLA-G induction." (PMID 30523283, 2018). "Cancers can also evade immune elimination by expressing non-classical MHC class I molecules (MHC Ib), such as HLA-E and HLA-G." (PMID 35892842, 2022). "The human leukocyte antigen-G (HLA-G), a member of the non-classical MHC family, inhibits the cancer immunity by abrogating NK cell activities." (PMID 31850199, 2019). "This study demonstrated that miR-19a or miR-19b-1 overexpression in cancer cells led to a general downward trend in the expression profile of MHC Class I molecules (such as HLA-B, HLA-E, HLA-F, HLA-G or HLA-J), which has never been reported in other physiological and pathological processes." (PMID 32308549, 2020). "Stratification of EV regarding their HLA-G content revealed that HLA-GEV could not be detected at all in some healthy donors, whereas levels increased with advanced cancer stages in EOC." (PMID 31382533, 2019). "Similarly, higher or comparable levels of expression of the non-classical genes, HLA-E, HLA-F, and HLA-G, were observed in HPV+ cancers with respect to normal control tissues in the HNSC cohort." (PMID 28891951, 2017).
infection (49 papers, 2012 to 2025). The state of being infected such as from the introduction of a foreign agent such as serum, vaccine, antigenic substance or organism. "A child, a mother or both genetically committed to produce high levels of HLA-G could be more susceptible to infections." (PMID 31235762, 2019). "In addition, several researchers have reported that reduced expression of HLA-G is linked to PE, and the HLA-G protein has been reported to be linked to spontaneous preterm birth and intra-amniotic inflammation or infections." (PMID 29540242, 2018). "The present result strengthens the hypothesis that the susceptibility of LBW children to infections could be associated with high sHLA-G levels, and that infants with LBW could have a particular mechanism of HLA-G regulation." (PMID 28166246, 2017). "Assaying soluble HLA-G at birth could be a good indicator of newborns more fragile and at risk of infections during childhood." (PMID 26862036, 2016). "Indeed, it has been shown that some polymorphisms of the HLA-G 3’UTR were associated with variable risk of infection, but also with antibody responses against P. falciparum." (PMID 26862036, 2016). "As IgG antibodies play a pivotal role in anti-malarial protection, the inhibition of IgG specifically directed against P. falciparum mediated by HLA-G, not only allows the parasite to escape the immune system but also is responsible of the higher susceptibility to infection showed previously." (PMID 26862036, 2016). "Collectively, the results emerging from the literature confirm the importance of the HLA-G molecule in the pathogenesis and progression of immune-based diseases and infections, underlining the relevance of its investigation with the aim to developing new therapeutic strategies and clinical markers." (PMID 25477881, 2014). "Dysregulated expression of HLA-G has been linked to diverse microenvironmental factors such as hypoxia, oxidative stress, nutrient deprivation and cytokines, all of which could be influenced by Mtb upon infection within the host." (PMID 39030302, 2024). "Evidence regarding HSV has shown that infection in trophoblasts disturbs the transport of antigens via HLA-G, which could affect the tolerance of immune cells and thereby generate mechanisms of damage to the maternal–fetal interface, culminating in infection-associated abortions." (PMID 38534983, 2024). "Consequently, the inhibition of IgG specifically directed against P. falciparum mediated by HLA-G may allow the parasite to escape the immune system and be responsible for higher susceptibility to infection." (PMID 28166246, 2017). "Due to the proposed function of HLA-G in placenta development, there must be an inverse association between HLA-G1 expression and uteri infection, such that, when HLA-G1 is down regulated in a HLA-G*0105N heterozygous placenta, this may enhance the intrauterine defense against infections." (PMID 27525330, 2016). "In our study, similar result was showed that the apoptosis of BeWo cells and primary trophoblast cells were positively with the up-regulation of HLA-G expression; meanwhile, IL-10 treatment could cause a decrease of HLA-G in early stage of infection with T. gondii." (PMID 23418570, 2013). "Of note, a minimal effect of infection on HLA‐G surface levels was perceived in MSR3 G1m cells, brightly stained by indirect IF with either G233, and anti‐HLA‐I W6/32." (PMID 40347012, 2025). "This dual functionality of HLA-G underscores its complex role in immunity, acting as both a suppressor in infections and tumors and a protector in specific contexts, such as immune-privileged sites." (PMID 40391199, 2025). "In some cases, the role of HLA-G in infections has been characterized to contribute to immune evasion of the infected host cells by inhibition of immune effector cells." (PMID 35237271, 2022).
infection (continued). "Infections with IAV are known to induce HLA-G mRNA and protein expression in alveolar epithelial cells, which is a major inhibitory molecule of host immune responses to IAV infections." (PMID 35237271, 2022). "In patients with severe infection, high serum levels of sHLA-G were observed and HLA-G was also found on the cell surface of diverse immune cells during the course of infection." (PMID 35237271, 2022). "HLA-G was detected on monocytes, T and B cells and showed a high-low-high pattern, probably correlating with infection, replication and clearance phase." (PMID 35237271, 2022). "In this model, early during the infection, S. Typhi is endocytosed by B cells, leading to HLA-G downregulation on their surface." (PMID 34659215, 2021). "We found that the percentage of B-LCL cells expressing HLA-G on their cell surface decreased as a function of the infection level." (PMID 34659215, 2021). "These current results will guide future investigations in the study of a new phenomenon, i.e., the study of regulatory mechanisms involving HLA-G in modulating MAIT cell responses to infections/pathogens." (PMID 34659215, 2021). "During infections HLA-G can be involved in immune escape of pathogens by creating a tolerogenic environment." (PMID 31235762, 2019). "In this review, we summarize the features of HLA-G expression by type of infections (i.e, bacterial, viral, or parasitic) detailing the state of knowledge for each pathogenic agent." (PMID 24839609, 2014). "We also discuss the cellular source of HLA-G, according to the type of infection and the potential role of HLA-G." (PMID 24839609, 2014). "HLA-G expression increases upon the in vitro infection of primary human trophoblasts and BeWo cells with Toxoplasma gondii, probably due to the secretion of proinflammatory cytokines in response to the parasite." (PMID 24839609, 2014). "There is evidence of upregulation of HLA-G mRNA in response to transformation, neovascularisation, inflammation, and infection." (PMID 24987709, 2014). "Maximum grade A rejection (RA), lymphocytic bronchiolitis (LB), maximum HLA-G concentrations (U/ml), and presence of infection in 38 subjects prior to onset of BOS." (PMID 25068264, 2014). "The polymorphism, the interference of viral proteins with HLA-G intracellular trafficking, and various cytokines have been described to modulate HLA-G expression during infections." (PMID 24839609, 2014). "Studies have focused on the expression of HLA-G in monocytes, which are relevant as reservoirs of HIV-1, and in lymphocytes, which are more susceptible to infection by HIV-1." (PMID 25477881, 2014). "Numerous studies have been conducted, aimed at observing the expression of the molecule HLA-G in the early stage of infection by HIV and its progression." (PMID 23841087, 2013). "The spearman's correlation analysis was used to quantitate the correlation between the HLA-G expression and apoptosis of human primary trophoblast cells and BeWo cells at 24 hr infection." (PMID 23418570, 2013). "The apoptosis of trophoblast cells and BeWo cells correlated positively with HLA-G at 24 hr infection of T. gondii (r = 0.733, P = 0.0142; r = 0.814, P = 0.0084)." (PMID 23418570, 2013). "In fact, it has been reported that HLA-G expression in cells is also upregulated following infection with human cytomegalovirus (CMV) and HIV." (PMID 23841087, 2013). "Since soluble HLA-G expression is also induced in stress and disease settings, such as tumors, transplantation sites, and during certain infections, it will be important to examine how NK cells and T cells respond to HLA-G at these sites." (PMID 22934097, 2012). "The immunological system microenvironment may influence the outcome of infection, as shown by HLA-G expression." (PMID 40953010, 2025). "The upregulation of HLA-G in viral and bacterial infections induce tolerance to infection." (PMID 35204759, 2022).